GLP1R (glucagon like peptide 1 receptor)
Diseases named in the same sentence as GLP1R in open-access papers (continued):
Sharing a sentence is not in itself a finding about the gene and the disease.
Hypoglycemia (continued). "Taking the GLP-1R agonist was associated with nausea, diarrhea, and vomiting, but not with hypoglycemia." (PMID 37266425, 2023). "Although the SGLT2 inhibitors/GLP-1-R agonists combination therapy may help in HbA1C and body weight reduction, hypoglycemia is more likely to occur compared to monotherapy." (PMID 37623335, 2023). "In particular, it opens up a promising methodology for a pre-screening of novel GLP-1R binders, which could reveal new pharmaceuticals to fight hypoglycemia." (PMID 36769142, 2023). "New drugs, such as sodium-glucose co-transporter inhibitors and glucagon-like peptide-1 receptor agonists that do not cause hypoglycemia and are associated with cardiovascular benefits, are available for the management of T2D." (PMID 37298308, 2023). "It should be taken into consideration that such an increased risk for hypoglycemia may be due to the simultaneous use of SGLT2 inhibitors and GLP-1-R agonists with other hypoglycemic agents, such as insulins or sulphonylureas, by some of the patients." (PMID 37623335, 2023). "Glucagon-like peptide 1 receptor agonist (GLP-1 RA) is a class of hypoglycemic medications that has shown benefit in glucose metabolism, beta-cell function enhancement, and weight loss promotion with a low risk of hypoglycemia." (PMID 34574899, 2021). "In special cases of endogenous hyperinsulinemic hypoglycemia (EHH), that is, in the context of MEN-1 or adult nesidioblastosis GLP-1R imaging is useful whereas in postprandial hypoglycemia in the context of bariatric surgery, GLP-1R imaging is probably not helpful." (PMID 31951592, 2020). "GLP-1R agonist therapies have low rates of hypoglycaemia and are also associated with weight loss and not weight gain (with current dosages used in therapies), which is an undesirable side effect of some other glucose-lowering therapies." (PMID 32269764, 2020). "To determine whether the GLP-1R agonist Ex-4 can counteract hypoglycaemia in NSC in vitro, we pre-treated NSCs with Ex-4 before adding low glucose for 24 hours." (PMID 27305000, 2016). "As might be expected of a glucose-dependent therapy, low incidences of hypoglycaemia were observed in clinical trials of exenatide QW, despite continuous exposure to the GLP-1R agonist due to extended release." (PMID 22776039, 2013). "Interestingly, SU-based compounds (such as glimepiride) have been observed to uncouple the glucose dependence of GLP-1R agonists and promote increased rates of hypoglycaemia in patients using GLP-1R agonists together with SU." (PMID 22776039, 2013). "Use of the GLP-1R agonists and DPP-4 inhibitors also enable the clinician to minimize the risk of some of the complications commonly encountered when treating patients with T2DM, such as hypoglycemia and weight gain." (PMID 22390369, 2012). "Therefore, we hypothesized that GLP-1RAs with high internalization rates could serve as potent fundamental precursors of GLP-1R imaging probes with a lower probability of inducing hypoglycemia in nuclear medicine diagnostics." (PMID 40076236, 2025). "If the insulin dose is minimal, it may be possible to discontinue insulin and switch to medications such as alpha-glucosidase inhibitors, dipeptidyl peptidase-4 (DPP-4) inhibitors, and glucagon-like peptide-1 receptor agonist (GLP-1RA)to manage blood sugar levels while also preventing hypoglycemia." (PMID 39575003, 2024). "Dipeptidyl peptidase-4 inhibitors (DPP-4i) and the glucagon-like peptide-1 receptor agonists (GLP-1 RAs) have become widely used in T2DM patients as a novel class of blood glucose–lowering drugs with improved weight loss, low risk for hypoglycemia, and reduction in glycated hemoglobin." (PMID 35847027, 2022). "However, when combined with a sulfonylurea, mild to moderate hypoglycemia has been reported by up to 36% of patients treated with the combination of a GLP-1R agonist or a DPP-4 inhibitor, which necessitates reducing the dose of the sulfonylurea, usually by half." (PMID 22390369, 2012).
Hypoglycemia (continued). "The glucagon-like peptide-1 receptor agonists (GLP-1 RAs) class agent has grown rapidly in the last decade due to its effects on lowering HbA1c and weight and the low possibility of hypoglycemia." (PMID 32481324, 2020). "Glucagon-like peptide 1 receptor agonists (GLP-1 RA) are attractive options, since they effectively reduce weight and improve blood glucose, without increasing the risk of hypoglycemia." (PMID 39996062, 2025). "By blocking GLP-1R, avexitide reduces postprandial insulin peaks and prevents hypoglycemia without significantly altering basal glucose levels." (PMID 41226200, 2025). "Tirzepatide, a dual GIP/GLP-1R agonist, demonstrated robust reductions in glycaemic control and body weight for the patients in the SURPASS studies, without causing hypoglycaemia." (PMID 35949358, 2022). "Several human clinical trials have demonstrated that patients using GLP-1R agonists and SU co-therapies have a greater incidence of hypoglycaemia than those not using SU." (PMID 22776039, 2013). "Tirzepatide is the first dual-target agonist that targets both the glucagon-like peptide-1 receptor (GLP-1R) and the glucose-dependent insulinotropic polypeptide (GIP) receptors, resulting in significant improvements in glucose control and weight without increasing the risk of hypoglycemia." (PMID 40667509, 2025). "Incretin-based therapies, GLP-1 receptor (GLP-1R) agonists and DPP-4 inhibitors, enhance the glucose-dependent insulin secretion and optimize the management of glycemic control without hypoglycemia and weight gain." (PMID 24884787, 2014). "Although, the specific GLP-1R agonist Ex-4 has been reported to stimulate NSC viability and to counteract NSC apoptosis both in vitro and in vivo, surprisingly, we could not achieve NSCs protection by Ex-4 in response to hypoglycaemia." (PMID 27305000, 2016).
Insulin resistance (159 papers, 2010 to 2026). Increased resistance towards insulin, that is, diminished effectiveness of insulin in reducing blood glucose levels. "Future studies should examine a personalized approach related to the management of weight loss or insulin resistance by investigating the benefits of newer medications (e.g., glucagon-like peptide-1 receptor agonists) in this population." (PMID 41359669, 2025). "Weight management is a key intervention for mitigating insulin resistance and T2D, and the widely used glucagon-like peptide-1 receptor agonists (GLP-1 RAs) are associated with an elevated risk of sarcopenia." (PMID 41515983, 2025). "The results provide important information for the mechanism underlying the function of GLP-1R on improving insulin resistance and related diseases." (PMID 28122026, 2017). "Besides, metformin has been shown to ameliorate neuronal insulin resistance in an in vitro neuronal insulin-resistant model also showing hallmark AD-like changes and to inhibit neuronal damage by upregulating GLP-1 receptor (GLP1R)." (PMID 39170185, 2024). "Neurodegenerative disorders, and AD in particular, are associated with T2DM-like metabolic abnormalities and insulin resistance in the brain, due to which intranasal insulin, insulin sensitizers, and GLP-1R agonists have been considered as potential therapeutic options in AD treatment." (PMID 35008973, 2022). "Indeed, among other effects, GLP-1R agonists promote weight loss, induce satiety, and reduce insulin resistance, effects that can all improve NAFLD independently of direct activation of hepatic GLP-1Rs." (PMID 34078383, 2021). "Nevertheless, we found moderate positive correlations between DRD1/DRD4 and GLP1R, especially in patients with insulin resistance, suggesting that GLP1R expression is associated with the decreased expression of dopamine receptors in patients with insulin resistance." (PMID 36768789, 2023). "Activation of GLP-1R not only improves dyslipidemia, insulin resistance, inflammatory responses, and hepatic steatosis, but also confers substantial cardiovascular and renal protective effects." (PMID 40496556, 2025). "Metformin can improve metabolic insulin resistance, while glucagon-like peptide-1 receptor agonists (GLP-1RAs) have the ability to stimulate insulin release." (PMID 41020901, 2025). "PCOS is a complex endocrine disorder characterized by hormonal imbalances, insulin resistance, and metabolic dysfunction, with androgens, incretins, and glucagon-like peptide-1 receptor (GLP-1R) signaling playing significant roles in its pathophysiology." (PMID 40076938, 2025). "There was compelling evidence that thiazolidinediones (TZDs) and glucagon-like peptide-1 receptor agonists (GLP-1Ras) were beneficial in treating MAFLD because they improved insulin resistance, control lipid metabolism, and dramatically lower body weight." (PMID 40431421, 2025). "Lifestyle practices that stimulate chronic excess insulin demand and secretion result in lower GLP-1 levels and, therefore, less GLP-1 receptor (GLP-1R) activation, which is associated with increased insulin resistance, obesity, and T2DM." (PMID 39062126, 2024). "The results open the way for larger cohort studies to further characterize the GLP-1R agonist-induced molecular changes and better understand the impact of these drugs on insulin resistance and inflammation in T2DM and its complications." (PMID 37686344, 2023). "Conversely, GLP1R gene expression and protein levels were described to be increased in the visceral adipose depot in obese patients with a high degree of insulin resistance." (PMID 36768789, 2023). "In the case of T2DM caused by β‐cell dysfunction or insulin resistance, synthetic agonist (glucagon‐like peptide GLP) targeting glucagon‐like peptide 1 receptor (GLP1R) showed promising therapeutic effects." (PMID 36721851, 2023).
Insulin resistance (continued). "For decades, the same approaches to treat T2D have been utilized largely revolving around various GLP-1R agonists and improving insulin resistance." (PMID 36030052, 2022). "The genetic variants related to T2DM in Caucasians are mainly related to insulin resistance, but those in Asians, including Chinese, Japanese, and Koreans, are involved in insulin secretion (GLP1R, PAX4, HNF4A, SLC30A8, HHEX, CDKAL1, CDKN2A/B, and GCKR)." (PMID 35956399, 2022). "In an insulin resistant HepG2 cell model, the PPARδ agonists enhanced exenatide efficacy on insulin resistance, with the expression of GLP-1R being up-regulated markedly." (PMID 36051387, 2022). "Glucagon-like peptide 1 receptor agonists (GLP-1 RAs) are a class of glucose-lowering drugs able to induce significant weight loss (on average 3–5 kg) and improve insulin resistance." (PMID 33652942, 2021). "Neonatal administration of exendin-4, an agonist of the glucagon-like peptide 1 receptor, has been previously shown to prevent hepatic oxidative stress in male offspring at 7–9 weeks of age, and in doing so mitigated hepatic insulin resistance." (PMID 34209700, 2021). "The T2D study revealed that the acute stimulation of GLP-1R did alter the myocardial glucose metabolism dependent on the baseline myocardial glucose metabolism and hence level of insulin resistance, consistent with the findings in the present study." (PMID 24400077, 2014). "Numerous methods and drugs have been designed to combat insulin resistance, including metformin, thiazolidinediones (TZDs), sodium-glucose cotransporter 2 inhibitors (SGLT2i), glucagon-like peptide 1 receptor agonists (GLP1RA), and dipeptidyl peptidase 4 inhibitors (DPP4i)." (PMID 39873298, 2025). "GLP-1R may ameliorate these conditions by improving insulin signaling and reducing insulin resistance in the brain." (PMID 40778306, 2025). "Moreover, it enhances glucose uptake in skeletal muscle cells under insulin resistance conditions through the Ca2+/calmodulin-dependent protein kinase II (CaMKII)/AMPK/GLUT4 signaling pathways in a GLP-1R-dependent manner." (PMID 41516048, 2025). "In addition, GLP-1R stimulation activates insulin signaling pathways and regulates gene expression, decreasing systemic insulin resistance and brain insulin resistance in patients with AD." (PMID 40778306, 2025). "GLP-1R agonists, by regulating insulin release and lowering blood glucose levels, may help improve insulin resistance and glucose metabolism disorders, indirectly protecting the nervous system from damage." (PMID 39719978, 2024). "With insulin resistance playing a major role in the pathogenesis of MetS, repurposing insulin sensitizers and incretins glucagon-like-peptide-1 receptor (GLP-1R)-agonists has become an accepted therapeutic strategy, particularly at the early stages of the disease." (PMID 39640841, 2024). "We also use our MPS to identify and characterize pharmacological intervention strategies for hepatic steatosis and systemic insulin resistance and find that the glucagon-like peptide-1 receptor agonist semaglutide improves hepatocyte function by acting specifically on adipocytes." (PMID 39266553, 2024). "The neuroprotective effects of GLP-1R agonists may be closely related to their impact on insulin resistance and glucose metabolism." (PMID 39719978, 2024). "As shown, GLP-1R agonists target three mechanisms involving reduced inflammation, reduced insulin resistance, and the control of glucose homeostasis, which could collectively result in the downregulation of non-collagen proteins." (PMID 37686344, 2023). "Moreover, we also observed the critical role of PPARδ in regulation of the expression of GLP-1R, the receptor for exenatide, and effects on insulin resistance." (PMID 36051387, 2022). "There may be a link between PPARδ and GLP-1R in the diabetic condition, which may be the molecular mechanism by which PPARD gene variants influence T2DM risk, insulin resistance and clinical response to exenatide." (PMID 36051387, 2022).
Insulin resistance (continued). "We next investigated whether GLP-1R agonists and L-dopa had an effect on the fasting plasma level of insulin, glucose, and the insulin resistance index (HOMA-IR) values." (PMID 34830228, 2021). "In individual patients with FPLD insulin secretion disruption or low dipeptidyl peptidase 4 (DPP4) levels were observed in addition to insulin resistance, suggesting the use of glucagon-like peptide 1 receptor agonists (GLP1) to improve glycemic control and reduce the high insulin demand." (PMID 33233602, 2020). "Counterintuitively, mice completely defective for the GLP-1 receptor were reported to be protected from high-fat diet-induced peripheral Insulin resistance and, consistently with this, central inhibition of GLP-1R signaling with the antagonist exendin 9-39 improves glucose tolerance and glycaemia." (PMID 30364192, 2018). "GLP-1R resistance in combination with insulin resistance cannot be excluded." (PMID 27941938, 2016). "However, in the context of established DM with significant insulin resistance, the incretin effect may be attenuated due to impaired insulin signaling or reduced GLP-1R responsiveness." (PMID 40732345, 2025). "Although it has been reported that excessive stimulation of β-ARs results in the induction of insulin resistance in many cell types, including cardiomyocytes, adipocytes, and skeletal muscle, prolonged overstimulation of GLP-1R has not been shown to cause these detrimental effects." (PMID 37375783, 2023). "Therefore, the PPARD risk mutations may serve as exenatide response predictors based on PPARδ regulating GLP-1R expression and mediating insulin resistance." (PMID 36051387, 2022). "Moreover, the common oral antidiabetic agents such as metformin, rosiglitazone, SGLT-2i (sodium dependent glucose transporters 2 inhibitor) and GLP-1RA (glucagon like peptide 1 receptor activation agents) have been widely used to improve insulin resistance in T2DM patients." (PMID 36204109, 2022). "Impaired activation of GIPR and GLP-1R contributes to a decrease in the secretion of insulin and ghrelin and, on the contrary, to an increase in leptin and glucagon in the circulation, which contributes to the formation of insulin resistance in obese patients with T2DM." (PMID 33959145, 2021). "Several types of antidiabetic drugs, including metformin, glucagon-like peptide-1 receptor agonists and dipeptidyl peptidase-4 inhibitors, were also associated with the normalization of enzyme levels in NAFLD by inhibiting liver inflammation and improving insulin resistance." (PMID 33971815, 2021). "Hence, the ability to increase GLP1R protein levels in pancreatic islets during early insulin resistance may be important to facilitate the compensatory increase in β-cell insulin secretion, maintaining normal glucose tolerance." (PMID 23781322, 2013). "Glucagon-like peptide-1 receptor agonists (GLP-1RAs) are central nervous system (CNS) penetrant and have shown to be neuroprotective against oxidative stress, neuroinflammation, and insulin resistance, as well as promoting neuroplasticity." (PMID 40485141, 2025). "Upregulating the expression of the glucagon-like peptide-1 receptor (GLP-1R), promoting the neogenesis of pancreatic β-cells, improving insulin resistance, and lowering blood glucose levels." (PMID 41189619, 2025). "It discusses the evidence supporting the use of glucagon-like peptide-1 receptor agonists (GLP-1RA) as potential adjunctive therapy in T1D to reduce weight and improve insulin resistance." (PMID 39906033, 2024). "According to our analysis, most studies consistently reported differential DNA methylation that affected PDX-1, GLP1R, PPARGC1A, etc., and thus led to insulin resistance." (PMID 37201099, 2023). "GLP1R, GNAS, and GCG were related to insulin resistance, which were verified by the previous studies." (PMID 36686441, 2022).
Insulin resistance (continued). "The main finding of the study was that weekly treatments of ExA for a duration of 6 weeks after the induction of diabetes improves cognitive impairment, insulin resistance, and hepatic steatosis via the activation of GLP-1/GLP-1R." (PMID 32079069, 2020). "But Glucagon-Like Peptide-1 Receptor Agonists (GLP-1 RAs) may represent an even more interesting pharmacological option for women with lipedema and insulin resistance." (PMID 40710038, 2025). "Glucagon-like peptide-1 receptor (GLP-1R) agonists lower body mass, insulin resistance, and steatosis without improving fibrosis." (PMID 37729871, 2023). "It upregulates glucagon‐like peptide‐1 receptor (GLP‐1R) expression in the pancreas, inhibits caspase family proteins and AIF, promoting β‐cell proliferation, preventing β‐cell apoptosis, increasing serum insulin levels, alleviating insulin resistance, and reducing fasting blood glucose." (PMID 40336535, 2025). "Liraglutide, a glucagon-like peptide-1 receptor agonist (GLP-1 RA), significantly reduces the incidence of major adverse cardiovascular events (MACE) in the LEADER trial, and has beneficial effects on insulin resistance, liver steatosis and dyslipidemia in T2D patients." (PMID 37143040, 2023). "The co-administration of L-dopa and exendin-4 also led to indicators of insulin resistance not seen with liraglutide, which may underpin the differential effects observed between the two GLP1-R agonists." (PMID 34830228, 2021). "Moreover, because GLP-1R is expressed throughout the body, stimulation with a GLP-1R agonist or indirectly with a DPP-IV inhibitor can have a broad systemic effect on systemic metabolism, which, in turn, ameliorates peripheral and central insulin resistance in AD and MD." (PMID 40778306, 2025).